HOTTIP (HOXA distal transcript antisense RNA)
Diseases named in the same sentence as HOTTIP in open-access papers (continued):
Sharing a sentence is not in itself a finding about the gene and the disease.
pancreatic cancer (46 papers, 2015 to 2025). "HOTTIP silencing or miR-137 upregulation promotes the susceptibility of pancreatic cancer cells to cisplatin, reducing proliferation and increasing apoptosis in these cells." (PMID 38559560, 2024). "In pancreatic cancer, lncRNA HOTTIP is highly expressed, and its high expression is associated with shorter overall survival and disease-free survival." (PMID 34821374, 2022). "We have previously reported that the lncRNAs HOTAIR and HOTTIP regulate expression of genes associated with pancreatic cancer cell proliferation, survival and migration." (PMID 29389953, 2018). "A few lncRNAs (HOTAIR, HULC, MALAT1, HOTTIP) have been found to be associated with pancreatic cancer." (PMID 28294968, 2017). "In pancreatic cancer, HOTTIP promotes progression and gemcitabine resistance by regulating HOXA1337." (PMID 40386064, 2025). "Specifically, HOTTIP increases the ability of pancreatic cancer cells to withstand both cisplatin and gemcitabine by either upregulating HOXA13 or downregulating miR-137, a miRNA that initially makes cells more sensitive to cisplatin." (PMID 40616679, 2025). "HOTTIP has been shown to control the proliferation, apoptosis, and migration of pancreatic cancer cells by regulating several HOX genes, including HOXA13, HOXA10, HOXB2, HOXA11, HOXA9, and HOXA1." (PMID 38559560, 2024). "HOTTIP also determines the pancreatic cancer cells’ resistance to gemcitabine, by overexpression of HOXA13." (PMID 38559560, 2024). "In pancreatic cancer, HOTTIP is also upregulated and imposes tumorigenic effects by the promotion of cancer growth, proliferation, migration, and metastasis." (PMID 36770654, 2023). "Stemness of pancreatic cancer cells is regulated by increased expression of HOTTIP, as a result of the production of stem cell factors such as NANOG, OCT4, and SOX2." (PMID 36770654, 2023). "The HOTTIP increases the resistance of pancreatic cancer cells to cisplatin by inhibiting miR-137, which increases the resistance of pancreatic cancer cells to cisplatin." (PMID 36770654, 2023). "Silencing of HOTTIP in these cells induces apoptosis and suppresses the growth and metastasis of pancreas tumor." (PMID 36770654, 2023). "High expression of HOTTIP in pancreatic cancer induced gemcitabine resistance while inhibition of HOTTIP potentiated anticancer activity of gemcitabine in vitro and in vivo." (PMID 34439315, 2021). "It was found that ectopic HOTTIP expression promoted growth and invasiveness in pancreatic ductal adenocarcinoma and that HOTTIP modulated pancreatic cancer stem cell properties by regulating HOXA9 epigenetically." (PMID 34439315, 2021). "Decreased expression of HOTTIP in pancreatic cancer cells leads to increased G0/G1 phase cells, decreased Vimentin and Snai1 expression, and increased E-cadherin expression." (PMID 32257946, 2020). "Several studies have demonstrated that HOTTIP is highly expressed in multiple cancers, including liver, kidney, lung, colorectal, and pancreatic cancer, and is involved in tumour progression." (PMID 32307830, 2020). "Compared with patients with lower expression, pancreatic cancer patients with higher HOTTIP expression had shorter disease-free survival and overall survival." (PMID 32441304, 2020). "Pioneering work in pancreatic cancer demonstrated the HOTTIP-targeted regulation of HOXA11 expression." (PMID 29415429, 2018). "HOTTIP has been proven to be correlated with the progression and prognosis of tongue squamous cell carcinoma, pancreatic cancer, osteosarcoma, and hepatocellular carcinoma." (PMID 30002503, 2018). "Actually, several lncRNAs including H19, MALAT1, UCA1, HOTTIP, have been reported to be involved in the chemoresistance of various kinds of malignant tumors, such as bladder cancer, pancreatic cancer, glioblastoma, and so on." (PMID 29069754, 2017).
pancreatic cancer (continued). "HOTTIP was observed to have pro-oncogenic functions in pancreatic cancer, similar to that of HOTAIR, although they elicit their effects through different pathways, leading to the expression of different sets of genes." (PMID 28294968, 2017). "In conclusion, our study suggested that PVT1, HOTTIP, MALAT1 was associated with the efficacy of first-line treatment with GEM based chemotherapy in pancreatic cancer." (PMID 29221115, 2017). "Overexpression of HOTTIP in human pancreatic cancers increases cell proliferation, invasion, and EMT activity." (PMID 27144338, 2016). "Another study shows that HOTTIP increases pancreatic cancer cell proliferation, survival, and migration through HoxA family genes other than HoxA13." (PMID 27144338, 2016). "Five well-documented lncRNAs: H19, HOTAIR, HOTTIP, MALAT1, PVT1, which are most closely associated with pancreatic cancer from previous studies were selected as putative lncRNA biomarkers." (PMID 27028998, 2016). "In the present study, HOXA13 was the most significantly inhibited gene within the HOXA locus following depletion of HOTTIP in pancreatic cancer cells." (PMID 25889214, 2015). "We also evaluated the expression of HOTTIP in five pancreatic cancer-derived cell lines (PANC-1, Capan-2, MIA PaCa-2, BxPC-3, and SW1990) and in immortalized human pancreatic ductal epithelial cells (HPDE6) by qRT-PCR." (PMID 25889214, 2015). "Our results also showed that HOTTIP regulated expression of multiple HOX genes in pancreatic cancer cell cells but, in contrast to results in liver cancer cell lines, HOTTIP did not regulate expression of HOXA13." (PMID 25912306, 2015). "In this study, we explored the role of HOTTIP in the regulation of proliferation, invasion, and chemoresistance of pancreatic cancer." (PMID 25889214, 2015). "HOTTIP is expressed in pancreatic cancer cell lines and knockdown of HOTTIP by RNA interference (siHOTTIP) in Panc1 pancreatic cancer cells decreased proliferation, induced apoptosis and decreased migration." (PMID 25912306, 2015). "In the present study, we investigated the expression and function of HOTTIP in pancreatic cancer cells and compared the results to that observed in previous studies on HOTAIR in pancreatic cancer cells." (PMID 25912306, 2015). "Furthermore, recent studies have shown that HOTTIP is specifically upregulated in small cell lung carcinoma, gastrointestinal cancer, pancreatic cancer, hepatocellular carcinoma, osteosarcoma, and ovarian cancer." (PMID 40624028, 2025). "HOTTIP modulates cancer stem cell properties in human pancreatic cancer by regulating HOXA9." (PMID 40624028, 2025). "For example, lncRNA HOTTIP mediates HOXA9 expression to enhance Wnt/β–catenin pathway activation by binding to WDR5 in pancreatic cancer stem cells (PCSCs), leading to upregulated expression of CSC markers (CD44, CD133, and ALDH1) as well as stem-associated factors (SOX2, OCT4, LIN28, and NANOG)." (PMID 39937018, 2025). "However, HOTTIP is supposed to be one of the predictors of response to chemotherapy in pancreatic cancer." (PMID 38559560, 2024). "Also, increasing the amount of PVT1 with MALAT1 and HOTTIP in serum has been suggested to predict the effect of gemcitabine in pancreatic cancer." (PMID 38559560, 2024). "HOTTIP could maintain the stemness of cancer stem cells (PCSCs) through the HOTTIP/WDR5/HOXA9/Wnt axis in pancreatic cancer; lncRNA H19 mediated the methotrexate resistance in colorectal cancer through activating Wnt/β-catenin signaling." (PMID 34690755, 2021). "Another lncRNA HOTTIP is also significantly upregulated in human pancreatic cancer." (PMID 34439315, 2021). "In pancreatic cancer, the LncRNA HOTTIP promoted gemcitabine resistance through modulating HOXA13." (PMID 32202509, 2020). "To date, a great number of studies have reported the role of HOTTIP in pancreatic cancers." (PMID 28818070, 2017).
pancreatic cancer (continued). "In addition, HOTTIP expression promotes cancer progression and drug resistance by regulating HoxA13 in pancreatic cancer." (PMID 27144338, 2016). "CCK-8 assays, colony formation assays, and xenografts in nude mice were used to investigate whether targeted silencing of HOTTIP could sensitize pancreatic cancer cells to gemcitabine." (PMID 25889214, 2015). "Moreover, for the first time, we identify an important role for HOTTIP in gemcitabine chemoresistance in pancreatic cancer cells." (PMID 25889214, 2015). "In addition to the HOTTIP-targeted regulation of HOXA13 expression, we also observed reduced HOTTIP levels upon siRNA-mediated knockdown of HOXA13 in two different pancreatic cancer cell lines." (PMID 25889214, 2015). "Functionally, HOTTIP silencing resulted in proliferation arrest by altering cell-cycle progression, and impaired cell invasion by inhibiting epithelial-mesenchymal transition in pancreatic cancer." (PMID 25889214, 2015). "In addition, the HOX gene targeted by in HOTTIP in pancreatic cancer cells are different from those regulated by HOTTIP in primary human fibroblasts." (PMID 25912306, 2015). "We have now investigated the role of HOTTIP in pancreatic cancer cells and have observed pro-oncogenic functions similar to that reported for HOTAIR, even though both lncRNAs elicit their effects by regulating expression of different sets of genes by different pathways." (PMID 25912306, 2015). "Thus, HOTTIP functions in pancreatic cancer cells are due, in part, to regulation of some HOX genes but not HOXA13 as previously observed in liver cancer cells." (PMID 25912306, 2015). "HOXA13 is more highly expressed than HOTTIP by over 2 orders of magnitude in all of the pancreatic cancer cell lines; however, despite these differences in the magnitude of expression, there was a correlation between expression of HOTTIP and HOXA13 in most of these cell lines." (PMID 25912306, 2015). "Furthermore, the high expression of HOTTIP is correlated with lymph node metastasis, indicating that HOTTIP may be a biomarker for lymph node metastasis in patients with pancreatic cancer and provide a basis for pancreatic cancer targeting therapy." (PMID 33937246, 2021). "In addition, HOTTIP can also mediate HOXA9 to enhance the stemness of pancreatic cancer cells." (PMID 32307830, 2020). "Thus, HOTTIP plays a pro-oncogenic role in pancreatic cancer cells." (PMID 25912306, 2015). "In another study, lncRNA HOTTIP was reported to modulate EMT and cell invasion as well as chemoresistance in pancreatic cancer by regulating HOXA13." (PMID 39937018, 2025). "One study showed that HOTTIP promotes EMT and regulates pancreatic cancer stem cells (CSCs) via induction of HOXA19 and then activation of Wnt pathway." (PMID 40616679, 2025). "HOTTIP is antisense to HOXA13 and modulates cancer stem cell properties in human pancreatic cancer by regulating HOXA9." (PMID 31890219, 2019). "Li and colleagues found that HOTTIP promotes progression and gemcitabine resistance by regulating HOXA13 in pancreatic cancer." (PMID 31528224, 2019). "The siRNA-mediated knockdown of HOTTIP resulted in a clear reduction of several HOX genes, particularly HOXA11 expression in Panc1 pancreatic cancer cells." (PMID 29415429, 2018). "The results suggest that MALAT1, HOTTIP and PVT1 as predictors to predict the efficacy of GEM based chemotherapy in first-line treatment of pancreatic cancer patients." (PMID 29221115, 2017). "Compared with benign pancreatic tumour (BPT) and normal pancreatic tissues (NPT), HOTAIR, HOTTIP and PVT1 were significantly up-regulated in pancreatic cancer tissues (PCT)." (PMID 27028998, 2016). "Compared with normal pancreatic tissues (NPT), the expression of HOTAIR, HOTTIP, and PVT1 exhibited significant elevation in pancreatic cancer tissues (PCT) (p values were 0.025, 0.006, and 0.016, respectively)." (PMID 27028998, 2016).
pancreatic cancer (continued). "Knockdown of HOTTIP by RNAi induced Annexin V staining and enhanced PARP cleavage in Panc1 cells, demonstrating that HOTTIP plays a role in pancreatic cancer cell survival." (PMID 25912306, 2015). "Results of knockdown and overexpression studies show that HOTTIP has functions comparable to that described for HOTAIR and plays a role in pancreatic cancer cell proliferation, survival and migration/invasion." (PMID 25912306, 2015). "The upregulation of HOTTIP/HOXA9 enhances the Wnt/β-catenin signaling pathway, whereas silencing of HOTTIP/HOXA9 reduces the expression of the Wnt protein family (Wnt1, Wnt3a, Wnt10a, and Wnt110b) in pancreatic cancer." (PMID 35819532, 2022). "Furthermore, HOTTIP knockout can reduce the expression level of HOXA13 and enhance the sensitivity of human pancreatic cancer cells to gemcitabine." (PMID 32257946, 2020). "In pancreatic cancer cells, HOTTIP regulates HOXA10, HOXB2, HOXA11, HOXA9 and HOXA1, but not HOXA13." (PMID 30819158, 2019). "Thus, results of this study confirm the pro-oncogenic activity of MALAT-1 in pancreatic cancer cells and demonstrate that this activity is distinct from that previously observed for HOTAIR and HOTTIP in Panc1 cells." (PMID 29389953, 2018). "Although the pro-oncogenic role of HOTTIP has been reported in some cancers including pancreatic cancer, non-SCLC, colorectal cancer, and so on6–11." (PMID 29367594, 2018). "Extensive research has proved the expression of HOTTIP is closely related to the occurrence and development of lung cancer and pancreatic cancer, whereas no data exist concerning the relationship between the expression of HOTTIP and epithelial ovarian cancer." (PMID 28818070, 2017). "We also observed that SMAD3, a negative prognostic factor for pancreatic cancer patients and gene that promotes epithelial-mesenchymal transition was also decreased after HOTTIP knockdown." (PMID 25912306, 2015). "Results of our study demonstrate a novel pro-oncogenic role for HOTTIP in pancreatic cancer cells, and we are currently investigating HOTTIP expression in tumors and both the HOX-dependent and -independent pro-oncogenic functions of HOTTIP in pancreatic and other cancer cell lines." (PMID 25912306, 2015). "However, the most striking observation was the minimal overlap between the genes regulated by HOTTIP vs. HOTAIR, further confirming the independent pro-oncogenic functions and gene regulation by these two lncRNAs in pancreatic cancer." (PMID 25912306, 2015). "Thus, our work confirms that the regulatory loop between HOTTIP and its target, HOXA13, is also preserved during pancreatic cancer tumorigenesis." (PMID 25889214, 2015). "Our results demonstrate that HOTTIP, which is overexpressed in human pancreatic cancer tissues and cells compared with non-tumoral tissues and cell lines, enhances pancreatic cell proliferation and invasion as well as EMT." (PMID 25889214, 2015). "Moreover, results of Boyden chamber and scratch assays show that knockdown of HOTTIP significantly decreased Panc1 cell migration and these results were similar to those previously observed in comparable experiments with HOTAIR in pancreatic cancer cells." (PMID 25912306, 2015). "In accordance, we observed that HOTTIP knockdown decreased the expression of several HOXA genes, particularly HOXA11 in a breast cancer-derived cell line, but in contrast to liver cancer cells and consistent with pancreatic cancer cells, HOTTIP does not regulate the expression of HOXA13." (PMID 29415429, 2018). "However, another study in pancreatic cancer cells demonstrated that HOTTIP did not modulate HOXA13 expression, but did regulate the expression of other HOX genes such as HOXA1, HOXA9, HOXA10, HOXA11 and HOXB2." (PMID 28938659, 2017). "Along with six other top DEGs, i.e. TINAG, LINC00460, UGT1A9, SLCO1B7, HOTTIP, and ALCO1B3, their expression status could not be found in the Pancreatic Cancer Database." (PMID 28418924, 2017).
pancreatic cancer (continued). "HOTTIP, which lies at the 5′ tip of the HOXA locus and drives H3K27me3 and gene transcription by binding with WDR/MLL complex, has been identified as a critical factor with tumor progression and drug resistance in pancreatic cancer and lung cancer without SCLC." (PMID 29041935, 2017).
ovarian carcinoma (25 papers, 2015 to 2025). A malignant neoplasm originating from the surface ovarian epithelium. "Another research showed that lncRNA HOTTIP is upregulated in ovarian cancer tissues and cell lines, and downregulation of lncRNA HOTTIP could cause pyroptosis, preventing the progression of ovarian cancer." (PMID 35896522, 2022). "Using paired cisplatin-sensitive and -resistant ovarian cancer cells, a study assessed the function of HOTTIP in the cisplatin resistance of these cells." (PMID 40616679, 2025). "HOTTIP silencing or miR-205 upregulation considerably increases the sensitivity of ovarian cancer cells." (PMID 39967908, 2025). "The HOTTIP/miR-206/TBX3 axis is involved in ovarian cancer cell stemness and cisplatin resistance development." (PMID 39967908, 2025). "Zinc finger E-box binding homeobox 2 (ZEB2) was ultimately shown to be the miR-205 gene target, completing the analysis of HOTTIP-miR-205-ZEB2 as the novel axis that is functionally engaged in determining the resistance of ovarian cancer cells to cisplatin." (PMID 40616679, 2025). "HOTTIP is also highly expressed in ovarian cancer cells and can promote the development of ovarian cancer and metastasis of ovarian cancer cells by regulating the transcription factor HIF-1α or pyroptosis." (PMID 39027044, 2024). "In the context of ovarian cancer, lncRNA HOTTIP has been verified to endow neutrophil-induced effector T cell apoptosis by boosting PD-L1 expression in neutrophils via activating the IL-6 signaling pathway by means of binding to c-jun in the nucleus." (PMID 37637063, 2023). "In ovarian cancer (OC), lncRNA HOTTIP significantly enhanced NLRP1 inflammasome-mediated pyroptosis via the miR-148a-3p/AKT2 axis." (PMID 36059539, 2022). "LncRNA HOTTIP is upregulated in ovarian cancer tissues, and microRNA-148a-3p was a downstream target gene of HOTTIP, exerting negative effects on the regulatory functions of HOTTIP." (PMID 35198448, 2022). "In particular, HOTTIP enhances IL-6 production and suppresses T cell activity, potentiating immunological escape of ovarian cancer cells." (PMID 36612180, 2022). "For instance, lncRNA HOTTIP induces the immune escape of ovarian cancer cells through up-regulation of PD-L1 in neutrophils." (PMID 34316393, 2021). "Regardless, we present compelling evidence for the role of HOTTIP-miR-205-ZEB2 axis in cisplatin resistance of ovarian cancer cells." (PMID 34322490, 2021). "Based on our findings, we believe that HOTTIP-miR-205-ZEB2 axis plays a critical role in cisplatin resistance of ovarian cancer cells." (PMID 34322490, 2021). "Through the use of these two independent cell lines, we have presented novel data for a role of HOTTIP in cisplatin resistant ovarian cancer cells." (PMID 34322490, 2021). "Nevertheless, the potential function of HOTTIP in ovarian cancer (OC), a prevalent cancer among women worldwide, remains elusive." (PMID 31533774, 2019). "The 5-prime end of HOXA includes three long non-coding RNAs (lncRNAs) (HOXA10-AS, HOXA11-AS, and HOTTIP) that are underexplored in epithelial ovarian cancer (EOC)." (PMID 26430965, 2015). "As an upregulated lncRNA in ovarian cancer tissues and cell lines, HOTTIP silencing leads to NLRP1 inflammasome-mediated pyroptosis, decreases cell viability, increases the expression of pro-pyroptosis factors, like IL-18, IL-1β, and NLRP1, and activates caspase-1 in ovarian cancer cells." (PMID 39967908, 2025). "Additionally, HOTTIP can potentially accelerate the immune escape of ovarian cancer cells by increasing IL-6-dependent PD-L1 expression." (PMID 40624028, 2025). "Either the upregulation of miR-615-3p or the downregulation of SMARCE1 could abrogate the tumor-promoting effect of HOTTIP in ovarian cancer." (PMID 37854681, 2023). "Additionally, in ovarian cancer, the silencing of HOTTIP led to NLRP1 inflammasome-mediated pyroptosis by focusing on miR-148a-3p/AKT2 axis as a target." (PMID 36281290, 2022).